HK2 (hexokinase 2)
Diseases named in the same sentence as HK2 in open-access papers (continued):
Sharing a sentence is not in itself a finding about the gene and the disease.
cancer (continued). "Furthermore, the protein levels of hexokinase 2, known for its upregulated expression in cancer cells, were significantly higher in 3D-cultured cells." (PMID 40280967, 2025). "Together with recent evidences showing that some key-glycolytic enzymes, such as GAPDH and PKM were able to regulate the translation of mRNAs in human T-cells and mouse embryonic stem cells, respectively, we explored the role of HK2 as an RBP regulating mRNA translation in human cancer cells." (PMID 40956859, 2025). "Furthermore, combining HK2 inhibitors with other therapies, such as immune checkpoint inhibitors, offers synergistic benefits, amplifying therapeutic efficacy by exploiting cancer-specific metabolic vulnerabilities." (PMID 40433363, 2025). "Key glycolytic enzymes such as hexokinase-2 (HK2) are overexpressed in many cancers." (PMID 41294748, 2025). "Notably, HK-2, PFKP, and PKM2 are closely linked to cancer cells, exhibiting significant upregulation in tumors." (PMID 40832602, 2025). "Indeed, previous mRNA analyses demonstrated a significant link between HK2 overexpression and highly glycolytic malignant tumors." (PMID 41450919, 2025). "3-BrPA directly inhibits HK2, thereby suppressing glycolytic flux in cancer cells." (PMID 40735327, 2025). "The activity of HK2 has been shown to play a key role in the progression of malignant tumors, with increased expression associated with poorer prognosis in GBM and various other cancers." (PMID 41450919, 2025). "For instance, hexokinase 2 inhibition with lonidamine did not significantly improve overall survival in several cancers, including breast and lung, and caused elevated toxicity." (PMID 40730548, 2025). "overexpression of HK-1 and HK-2 likewise has pro-cancer effects." (PMID 40165895, 2025). "Moreover, HK2 contributes to apoptosis evasion in cancer cells by binding to VDAC1 and competing with Bax." (PMID 40941984, 2025). "HK2 inhibition restricts cancer cell growth by limiting ATP access for glucose phosphorylation." (PMID 40941984, 2025). "While glucose transporters primarily enhance glucose uptake, HK2 engineering provides a broader metabolic advantage by increasing glycolytic and mitochondrial fitness, offering a complementary approach to improving T-cell efficacy in cancer immunotherapy." (PMID 40181966, 2025). "HK2 has been recognized for its role in apoptosis in several cancers." (PMID 40643524, 2025). "In conclusion, the potential of targeting HK2 for cancer therapy is promising, and with these challenges addressed, natural products inhibiting HK2 will play an even greater role in the fight against cancer." (PMID 39991762, 2025). "Hexokinase 2 (HK2), enriched at MAMs, exhibits elevated expression levels in cancer cells." (PMID 40661148, 2025). "In conclusion, HK2 represents a promising therapeutic target for cancer treatment." (PMID 39991762, 2025). "We identified a robust upregulation of GLUT1 (SLC2A1), a key rate-limiting factor in the transport of glucose in cancer cells, and genes involved in central glucose metabolism (HK2, ENO1, PKM, and LDHA), PPP (G6PD), and de novo serine biosynthesis pathway (PSAT1, PSPH, and SHMT2)." (PMID 40371988, 2025). "As HK2 is a critical enzyme in the regulation of glycolysis in cancer cells, we next investigated whether HK2 was involved in the inhibition of ADAMTS9-AS2-regulated glycolysis in OSCC cells." (PMID 40831535, 2025). "Simultaneous targeting of HK2 and complex I can induce energetic crisis in cancer cells." (PMID 40469185, 2025). "We investigated whether HK2 contributes to cancer-related phenotypes by modulating SOX10 mRNA translation." (PMID 40956859, 2025). "B7-H3 may also enhance glucose metabolism in cancer cells by promoting the expression of hexokinase 2 (HK2)." (PMID 40214484, 2025). "Enzymes like LDHA and HK2, crucial for lactate production, are overexpressed in many cancers." (PMID 40433363, 2025).
cancer (continued). "Additionally, Bayogenin showed a strong interaction with Hexokinase 2 (HK2), a key enzyme involved in cancer cell metabolism." (PMID 40739477, 2025). "Taking HK2 as the target of cancer therapy provides a new idea to break through the cancer problem." (PMID 38590647, 2024). "It is important to note that forced overexpression of HK2 triggers cancer cell invasiveness." (PMID 38383348, 2024). "Inhibiting HK2 activities could directly target the metabolic alterations in cancer cells, particularly disrupting the aberrantly facilitated glycolysis." (PMID 39713255, 2024). "Cancer therapy could potentially benefit from targeting HK2, a vital enzyme involved in aerobic glycolysis that is frequently upregulated in cancer cells." (PMID 39224810, 2024). "HK2 activity is heightened with metabolic stress and maintains cancer stem cell potency." (PMID 39028417, 2024). "However, targeting yeast cells with 2-deoxy-D-glucose (2-DG), a HK2 inhibitor that has been proposed as an anti-cancer treatment, significantly increased chromatin instability." (PMID 38352584, 2024). "Notably, these genes, such as PPARG, HK2, and PDK1, play critical roles in the regulation of aerobic glycolysis in cancer cells, which is associated with the IDH phenotype in GBM cells." (PMID 39530009, 2024). "Consequently, targeting HK2 has emerged as a promising adjunctive therapy to disrupt the metabolic rewiring of cancer cells." (PMID 39713255, 2024). "HK2 is elevated in malignant tumors and promotes the glycolytic phenotype in cancers." (PMID 39594816, 2024). "Whether utilizing carriers for HK2 shRNA nanoparticles or employing intraperitoneal injection of radioactive anti-cancer agents, both approaches enhance therapeutic efficacy and improve patient survival rates." (PMID 38577616, 2024). "Thus, small molecule inhibitors targeting HK2 were explored as potential targets for cancer therapy." (PMID 38041756, 2024). "LINC02432 lncRNA may regulate HK2 and ferroptosis in cancer, which may contribute to the evidence that decidualization involves metabolic reprogramming and an increased reliance on aerobic glycolysis." (PMID 38727314, 2024). "Intriguingly, the exact three glycolytic genes with the highest upregulation upon ESCRT-I deficiency (encoding HK2, ENO2 and PFKFB3) were reported to have increased expression in cancer-associated fibroblasts due to activation of JNK signaling upon compression-induced stress." (PMID 39560723, 2024). "Among them, HK2 is a specific downstream target of Akt in cancer 22-30." (PMID 38904014, 2024). "This study provides valuable insights for potential therapeutic strategies that can enhance the anticancer efficacy of TCS by targeting HK2, suggesting that modulating aberrant glycolysis holds a promise to enhance the sensitivity of cancer cell to TCS-based therapeutic strategy." (PMID 39713255, 2024). "This elucidates the potential of HK2 inhibitionin reducing cancer cell proliferation." (PMID 38829285, 2024). "For example, HK1 plays an oncogenic role in bladder cancer, and HK2 enhances live cancer stemness." (PMID 39192292, 2024). "Moreover, 18F-FDG PET serves as a diagnostic tool to assess the effectiveness of cancer cell treatment through fibroblast growth factor receptors (FGFR)-targeted therapy, which is activated by FGFR and mTOR/HK2 axis." (PMID 38974238, 2024). "Here, we find that MPNSTs express high levels of the glycolytic enzyme Hexokinase 2 (HK2), which is known to shield cancer cells from noxious stimuli when it localizes at MAMs (mitochondria-associated membranes), contact sites between mitochondria and endoplasmic reticulum." (PMID 38995012, 2024). "Similarly, targeting HK2 can affect glucose and fructose metabolism, making it a broad-spectrum strategy against cancer cells." (PMID 39107723, 2024).
cancer (continued). "Notably, HK2 is overexpressed in many aggressive tumors and localized to mitochondrial outer membrane attaining higher conformational stability compared to cytosolic HK2 suggesting, HK2 as a novel target for drug discovery against a multitude of cancers." (PMID 38529190, 2024). "Among four HK isoforms, HK2 is overexpressed in many cancer cells." (PMID 38495480, 2024). "Additionally, HK2 protects cancer cells from apoptosis by docking to mitochondria and inhibits cell death by regulating the mitochondria-mediated intrinsic pathway." (PMID 39136001, 2024). "Furthermore, in the existing studies, HK2 was shown to be upregulated in multiple types of cancers and correlated with increased aerobic glycolysis." (PMID 36837559, 2023). "Experiments with cancer cells also indicate that Nrf2 may upregulate the expression of HK2, which may allow higher glycolytic rates." (PMID 37666117, 2023). "Although the mitochondrial binding property of HK2 appears to be in tune with the metabolic demands of cancer cells, allowing them to couple glucose consumption with energy (ATP) production, its role in mediating glucose consumption and anabolic processes under normal conditions remains elusive." (PMID 37109475, 2023). "Thus, HK2 serves as a favorable target for cancer therapy and a rate-limiting step for the glycolysis pathway." (PMID 37762231, 2023). "Moreover, available information suggests that several other TRAF3-regulated metabolic enzymes (e. g., Lpcat1, Pygl, Hk2, and Mthfd1) are also targetable points in cancers." (PMID 36776285, 2023). "In addition to the ubiquitously expressed HK1, cancer cells overexpress HK2, which is critical to the Warburg effect because phosphorylated glucose is trapped in the cytoplasm." (PMID 37164974, 2023). "HK2 is highly expressed in lung and breast cancer and required for the proliferating cancer cells." (PMID 36614197, 2023). "Another methyltransferase VIRMA increases the methylation level of HK2 mRNA in an m6A-dependent manner, up-regulates the level of HK2 mRNA and improves its mRNA stability, which can ultimately accelerate the aerobic glycolysis of cancer cells and improve the degree of malignancy." (PMID 37582735, 2023). "The mitochondrial-bound HK2 is therefore elevated in many forms of cancer." (PMID 37109475, 2023). "In many cancer cells, the Type II isoform of hexokinase (HK2) is overexpressed." (PMID 36906698, 2023). "HK2 plays a role in the metabolic shift towards aerobic glycolysis in cancer cells." (PMID 37446908, 2023). "HK2 is commonly upregulated in various cancers and exerts pro-cancer properties." (PMID 37524692, 2023). "Furthermore, BIS directly regulates metabolism by stabilizing hexokinase 2 mRNA and glutaminase in cancer cells." (PMID 37298584, 2023). "Numerous studies have reported that HK2 in cancer cells promote immune evasion." (PMID 37524692, 2023). "Therefore, development of anti-cancer drugs that target HK2 for inhibition of glycolysis and induction of apoptosis has been reported." (PMID 36609747, 2023). "In fact, elevated HK2 expression seems to be correlated with cancer aggressiveness, progression, dissemination, and shorter disease-free and overall survival, being independently validated as a poor prognosis biomarker in two meta-analyses on gastrointestinal tumours." (PMID 36765947, 2023). "2-DG also demonstrates a wide range of anti-cancer effects through the inhibition of HK2 activity." (PMID 36984785, 2023). "The expression level of HK2 is significantly increased in several cancers." (PMID 36994237, 2023). "HK2 expression in these cancers inversely correlates to overall patient survival rates." (PMID 37109475, 2023). "HK2, a key member of the HK family, catalyzes the first committed step in glucose metabolism by phosphorylating glucose, and it is specifically expressed in many foetal tissues and cancer cells." (PMID 38082439, 2023).
cancer (continued). "Interestingly, HK2 levels increased gradually with the progression of cancer stages in patients with DLBCL." (PMID 37854321, 2023). "HK2 is closely related to the Warburg effect in cancer cells." (PMID 37834257, 2023). "In addition, although it has been demonstrated that HK2 can accumulate in the nucleus of cancer cells, the exact function of nuclear HK2 remains incompletely understood." (PMID 38203486, 2023). "3-bromopyruvate (3-BrPA) exerts anti-cancer effects by targeting HK2." (PMID 36984785, 2023). "Given HK-2's dual function in cancer cells, it is an attractive target for anticancer therapies." (PMID 38114977, 2023). "In cancer, HK2 is extensively modified by deubiquitinases and ubiquitinases." (PMID 37190313, 2023). "The mammalian target of rapamycin (mTOR) pathway is a crucial pivot in cancer promotion and the mTOR-miR-143/HK2 axis could accelerate tumor proliferation and formation by promoting glucose metabolism in lung cancer." (PMID 37208722, 2023). "HK2 promotes cancer cell growth, migration, invasion, and metastasis." (PMID 37019900, 2023). "Furthermore, the PI3K-AKT pathway has been reported to be involved in glucose metabolism, particularly in regulating GLUT1 and hexokinase 2 to mediate glycolysis in various types of cancer." (PMID 38057829, 2023). "Several cancers show negative correlation of AHR promoter methylation with HK2 expression, which was associated with worse overall patient survival." (PMID 37696456, 2023). "However, the physiological significance of HK2 inhibitors and mechanisms of HK2 inhibition in cancer cells remain largely unclear." (PMID 37019900, 2023). "Formalin-fixed tissues were immunostained for hexokinase-2 (HK2) to assess cancer cell glycolysis." (PMID 36320008, 2022). "HK2 helps immortalize cancer cells and escapes chemotherapy inhibition." (PMID 36335239, 2022). "Considering the FGFR aberration usually activates AKT-mTOR, PLCγ, and MEK-ERK pathways in cancer 1,2, we used the selective inhibitors or specific siRNAs to block these downstream signalings to test which could downregulate HK2." (PMID 36168616, 2022). "It has four important isoforms, in which, HK2 is the prominent isoform in the cancer cells." (PMID 36230935, 2022). "However, when normal cells are converted to cancer cells, they start expressing very high levels of HK2 in addition to the already expressed HK1." (PMID 35173161, 2022). "In addition, HK2 expression was upregulated in CRC tissues, and a vast number of studies showed that aberrant expression of HK2 enhances cancer cell malignant transformation in various types of cancers." (PMID 36232922, 2022). "Besides, HK2 has been recognized to regulate the malignant phenotype of cancer cells, such as cellular apoptosis and migratory capabilities." (PMID 36072431, 2022). "Inhibition of LDHA and HK2 expression suppresses the Warburg effect in cancer cells." (PMID 35256924, 2022). "However, the acceleration of anabolism in cancer cells requires stronger HK activity; thus, HK2 expresses in the greater amount." (PMID 35265223, 2022). "Similarly, cancer patients of all ages predominantly expressed higher levels of HK2 compared with normal individuals." (PMID 35265223, 2022). "HK2 is upregulated in cancer cells and is the major gene contributing to Warburg glycolysis." (PMID 36193432, 2022). "Hexokinase 2 (HK2), an enzyme of the sugar kinase family, plays a dual role in glucose metabolism and mediating cancer cell apoptosis, making it an attractive target for cancer therapy." (PMID 35269760, 2022). "Furthermore, the high expression of HK2 in cancer tissue cells is directly related to DNA methylation." (PMID 36230492, 2022). "Some studies indicated that lncRNA could act as a sponge of miRNA, enhance the expression of HK2, and promote cancer cell proliferation, metastasis, and invasion." (PMID 36072431, 2022).
cancer (continued). "The effect obtained against cancer cells may be related to the fact that inhibition of HK2 may lead to the formation of mitochondrial permeability pores and unblock the recruitment of mitochondrial proapoptotic proteins such as Bax and Bak." (PMID 35269760, 2022). "According to the expression levels of HK2, we divided the cancer cases into high-expression and lower-expression groups and investigated the correlation of HK2 expression with the prognosis of patients with different tumors, mainly using the datasets of TCGA and GEO, respectively." (PMID 36335239, 2022). "Our results demonstrated that HK2 was highly expressed in most malignant cancers." (PMID 35982398, 2022). "Thus, HK2 is a critical regulator of the Warburg effect and is now emerging as an important target for cancer metabolism." (PMID 36013278, 2022). "Because HK2 overexpression has been found in a variety of cancers, it could be used as a therapeutic target in cancer treatment." (PMID 36276846, 2022). "Therefore, we used the TIMER, CIBERSORT, CIBERSORT-ABS, TIDE, XCELL, MCPCOUNTER, and EPIC algorithms to explore the potential relationship between the infiltration of immune cells and HK2 gene expression in different cancer types of TCGA." (PMID 36335239, 2022). "The TIMER2 database was used to analyze the expression of HK2 in various cancers of TCGA." (PMID 36335239, 2022). "Hexokinase 2 (HK2) is one of the key factors involved in the development of several human cancers." (PMID 35265223, 2022). "The disturbed glucose metabolism, as metabolic vulnerability for FGFR-addicted cancers, especially the corresponding expressional change of HK2, the key rate-limiting glycolytic enzyme, allows us trying to monitor the FGFRi-response by 18F-FDG (an analog of glucose) PET imaging." (PMID 36168616, 2022). "This indicated that the dysregulation of HK2 is a common event in human cancer and may play a key role in cancer development and progression." (PMID 35603967, 2022). "HK2 overexpression was found to be highly significant in these malignant tumors." (PMID 35328104, 2022). "HK2 is overexpressed in a variety of tumors and is a characteristic feature of cancer cells." (PMID 36013278, 2022). "Previous studies have shown that HK2 is essential for glucose metabolism in various cancers." (PMID 35379058, 2022). "There is now interest to inhibit HK2 in cancer cells and xenograft models." (PMID 36712976, 2022). "HK2 is one of the major frontline enzymes required for glycolysis and cancer cell survival." (PMID 35260660, 2022). "Among the different subtypes of cancers, the expression of HK2 is diverse." (PMID 36072431, 2022). "Although these metabolic genes were not correlated with age in several cancer cohorts, a statistically significant association of HK2 and PFKM gene overexpression with age was observed in our data." (PMID 35328104, 2022). "Elevated expression of hexokinase 2 (HK2) has been identified in several cancers." (PMID 35335873, 2022). "Different hexokinases are expressed in a tissue-specific manner, and only HK2 is overexpressed in cancer cells, which might contribute to the high glycolytic rate in tumors." (PMID 35457018, 2022). "To underpin the role behind the reduction in the glucose fermentation rate in TQ-treated CRC cells, we evaluated the expression status of HK2, the first rate-limiting enzyme of glucose metabolism and an enzyme highly overexpressed in most cancers including CRC." (PMID 35216429, 2022). "Given that HK2 inhibition sensitizes cancer cells to multiple chemotherapy agents, we speculated that HK2 SUMOylation may play roles in docetaxel treatment response." (PMID 33753739, 2021). "Thus, an increasing number of studies on cancer metabolism are examining the regulation of HK2 expression as a promising anticancer strategy." (PMID 34047477, 2021). "In other experiments, the silencing of HK2 reduced lung metastasis in several cancer models." (PMID 35029792, 2021).